HMOX1 (heme oxygenase 1)
Diseases named in the same sentence as HMOX1 in open-access papers (continued):
Sharing a sentence is not in itself a finding about the gene and the disease.
fibrosarcoma (26 papers, 2015 to 2025). A malignant mesenchymal fibroblastic neoplasm affecting the soft tissue and bone. "Heme oxygenase-1 (HO-1), a main source of intracellular iron, has been proven to play a decisive role in erastin-induced ferroptosis, and the inhibition of HO-1 prevents erastin-triggered ferroptosis in HT-1080 fibrosarcoma cells." (PMID 37325669, 2023). "This is in line with the fact that HMOX1 is elevated in various human malignancies such as, for example, fibrosarcoma tumors and HT1080 cells." (PMID 36899871, 2023). "The Heme Oxygenase 1 (HO-1), Serine hydrolase inhibitor, and LOX15 activator induced ferroptosis in fibrosarcoma cells respectively by causing intracellular iron overload, ROS accumulation, and accelerating lipid peroxidation." (PMID 36457488, 2022). "Consistently, HMOX1 knockout has been found to suppress ferroptosis, whereas HMOX1 overexpression accelerates ferroptosis in HT-1080 fibrosarcoma cells." (PMID 36147464, 2022). "Similarly, in human fibrosarcoma cells, the activation of HMOX-1 facilitates the accumulation of lipid peroxidation under oxidative stress, which further sensitizes the cells to erastin-induced ferroptosis." (PMID 41509286, 2025). "Moreover, heme oxygenase 1 (HO-1) overexpression in HT-1080 fibrosarcoma cells exacerbates ergocalin-triggered cell death." (PMID 39434776, 2024). "At the same time, the active role of HMOX1 in tumor cells constitutes a significant difference compared to the healthy tissue and is, consequently, a way by which compounds such as nemorosone could induce a selective ferroptosis mechanism in cancer cells such as fibrosarcoma." (PMID 36899871, 2023). "Subsequently, the transcription regulator protein BACH1-transcription factor musculoaponeurotic fibrosarcoma (MAF) complex, which suppresses the expression of HO-1, is dissociated, releasing MAF, which binds with Nrf2 and induces HMOX1 transcription." (PMID 34452191, 2021).
acute lung injury (25 papers, 2013 to 2026). A condition of lung damage that is characterized by bilateral pulmonary infiltrates (pulmonary edema) rich in neutrophils, and in the absence of clinical heart failure. "Heme oxygenase 1 (HO-1) plays a critical protective role in various insults-induced acute lung injuries (ALIs) through its strong anti-oxidant properties." (PMID 36290735, 2022). "In addition to lung development, roxadustat can relieve airway inflammation and protect against acute lung injury (ALI) by increasing heme oxygenase-1 (HO-1) expression and decreasing tumor necrosis factor-α and interleukin-1β production." (PMID 36724056, 2023). "In lipopolysaccharide (LPS)-stimulated murine macrophages RAW264.7 and in mice with LPS-stimulated acute lung injury (ALI), 5 and 10 μg/ml AIF significantly increased the production of antioxidative enzymes such as catalase, heme oxygenase-1 (HO-1), glutathione peroxidase, and superoxide dismutase." (PMID 31551770, 2019).
epilepsy (25 papers, 2020 to 2025). A brain disorder characterized by episodes of abnormally increased neuronal discharge resulting in transient episodes of sensory or motor neurological dysfunction, or psychic dysfunction. "This is further evidenced by the pentylenetetrazole (PTZ) kindled mouse model of epilepsy which produces significant neuronal cell loss associated with oxidative stress, lipid peroxidation and enhanced hippocampal HMOX1 expression." (PMID 38166692, 2024). "In summary, these findings suggest that PX-478 has the potential to treat epilepsy by inhibiting the hypoxia-inducible factor 1α/heme oxygenase-1 pathway, alleviating oxidative stress, and reducing ferroptosis in hippocampal neurons." (PMID 39995090, 2025). "Our results suggested that glycitin exerts a protective effect on PTZ induced epilepsy by obvious upregulation of Nrf2 and Hmox1 genes expression." (PMID 39246658, 2024). "In this research, we identified six characteristic genes associated with ferroptosis in epilepsy: NFE2L2, PTGS2, IL6, JUN, HMOX1, and TLR4." (PMID 37946105, 2023). "We have identified six feature genes (IL6, PTGS2, HMOX1, NFE2L2, TLR4, and JUN) strongly associated with ferroptosis in epilepsy, suggesting their potential as biomarkers for the diagnosis of temporal lobe epilepsy." (PMID 37946105, 2023). "In epilepsy models using rats with induced seizures, chrysin counteracted oxidative stress, reduced neuronal apoptosis, and increased expression of nuclear factor erythroid 2-related factor 2 (Nrf2) and heme oxygenase-1 (HO-1)." (PMID 40872553, 2025). "Based on the present results, ferroptosis-related hub genes NFE2L2, PTGS2, IL6, JUN, HMOX1, and TLR4 have good diagnostic value for epilepsy and may be potential early biological diagnostic targets." (PMID 37946105, 2023).
liver cancer (25 papers, 2011 to 2026). An epithelial or non-epithelial malignant neoplasm that arises from the liver. "GSK-J4 and donafenib synergistically facilitate the expression of HMOX1 and enhance intracellular ferrous iron level, finally causing ferroptosis in liver cancer." (PMID 39827156, 2025). "The 14 liver injury-associated oleanolic acid targets also had low somatic mutation rates in cancer, and HMOX1 had a 1% somatic mutation rate in liver cancer compared to a 5% mutation rate in cancer as a whole." (PMID 38127054, 2023). "Based on RNA-seq data from 968 liver cancer-related patients, we explored the effect of the HMOX1 gene on iron death-related genes." (PMID 38127054, 2023). "This all suggests that HMOX1 can promote high expression of Ferroptosis promoting genes and promotes Ferroptosis of liver cancer." (PMID 38127054, 2023). "Fourteen liver-damaging oleanolic acid targets were generally lowly expressed in cancer and HMOX1 was lowly expressed in liver cancer." (PMID 38127054, 2023). "This suggest that HDAC1 and HMOX1 are important targets of oleanolic acid for liver cancer inhibition." (PMID 38127054, 2023). "Remarkably, Reactome enrichment analysis suggested that genes pertaining to PTK6 expression and the regulation of HMOX1 expression and activity could represent one of the mechanisms through which metformin acts in the treatment of liver cancer." (PMID 40583627, 2025). "Our study also found that oleanolic acid in liver cancer could promote the development of Ferroptosis in liver cancer by promoting HMOX1." (PMID 38127054, 2023). "And we determined that HMOX1 promotes Ferroptosis in liver cancer." (PMID 38127054, 2023). "In liver cancer, we identified that the main target of oleanolic acid is HMOX1 and HDAC1." (PMID 38127054, 2023). "It suggested that HMOX-1 is a protective gene in liver cancer." (PMID 35069936, 2022). "Using sequencing data related to liver cancer and cirrhosis, we found that HDAC1 and HDAC2 expression was elevated in liver cancer and cirrhosis, and HMOX1 and HMOX2 expression was decreased." (PMID 38127054, 2023). "In this study, we first found that curcumin induced changes in the expression of CYP1A1, HMGCS2, HMOX1, LCN2, and MTTP, which are enriched in metal ion homeostasis, in all three liver cancer cell lines." (PMID 36838613, 2023). "Using oleanolic acid-related liver cancer sequencing data, we found that oleanolic acid decreased the expression of HDAC1 and HDAC2 and increased the expression of HMOX1 and HMOX2." (PMID 38127054, 2023).
chronic obstructive pulmonary disease (23 papers, 2008 to 2025). A chronic and progressive lung disorder characterized by the loss of elasticity of the bronchial tree and the air sacs, destruction of the air sacs wall, thickening of the bronchial wall, and mucous accumulation in the bronchial tree. "Given these functions of HMOX1, it has been implicated in a variety of pathological states, including myocardial infarction, diabetes, chronic obstructive pulmonary disease (COPD)." (PMID 32899231, 2020). "Heme oxygenase 1 (HMOX1) plays an important role in the development of chronic obstructive pulmonary disease (COPD)." (PMID 27998018, 2017). "This study examined the effect of the nuclear factor erythroid 2-related factor 2 (Nrf2)/heme oxygenase 1 (HO-1) pathway on chronic obstructive pulmonary disease (COPD) and the potential molecular mechanism." (PMID 38317168, 2024).
hematoma (23 papers, 2016 to 2026). A hematoma is a collection of blood from a vascular structure into an extravascular space. "HMOX1 has been reported to be expressed in microglia, and microglial HMOX1 induction after hemorrhagic stroke was positively associated with hematoma size." (PMID 37529171, 2023). "Multivariate logistic regression analysis revealed that increased NIHSS scores, elevated hs-CRP levels, cerebral lobe or cerebellar hemorrhage, larger hematoma volume, and higher HMOX1 mRNA expression were independent risk factors for poor prognosis (all P < 0.05)." (PMID 41404462, 2025). "The index tests were HMOX1 mRNA levels and early imaging parameters (hemorrhage location, hematoma volume, and shape), with the reference standard being the 90-day mRS score." (PMID 41404462, 2025). "Within the clinically relevant threshold probability range (0.01–0.5), the multivariable model's net benefit was consistently higher than that of HMOX1 mRNA alone, hematoma volume alone, and extreme strategies." (PMID 41404462, 2025). "We will measure HMOX1 mRNA levels in peripheral blood and analyze early imaging parameters, including hemorrhage location, hematoma volume, and shape, using CT scans." (PMID 41404462, 2025). "FKN improves microglial erythrophagocytosis via the CD163/heme oxygenase-1 (HO-1) axis, thus mitigating neuroinflammation, hematoma size and Hb content and relieving neurological deficits in ICH mice." (PMID 40661949, 2025). "A nomogram model for predicting poor prognosis in HICH patients was constructed using the NIHSS score, GCS score, creatinine level, hs-CRP level, hemorrhage location, hematoma volume, and HMOX1 mRNA level as predictive factors." (PMID 41404462, 2025). "Hierarchical lines 3, 4, 5, 6, and 8 included creatinine, hs-CRP, hemorrhage location, hematoma volume, and HMOX1 mRNA as independent variables, respectively." (PMID 41404462, 2025). "In particular, genetic ablation of CDNF markedly impaired hemorrhagic lesion resolution and downregulated Hmox1 transcription at the phase of hematoma accumulation." (PMID 36792604, 2023). "Heme oxygenase-1 (HO-1) plays a significant role in the degradation of pro-oxidant heme, and the Hb/haptoglobin-CD163-HO-1 system contributes to hematoma clearance and defense against Hb neurotoxicity as well as erythrophagocytosis." (PMID 35410231, 2022). "Hematoma pATF1 activation was prevented in AMPK knockouts, resulting in loss of Hmox1 induction, with promotion of inflammation and oxidative stress." (PMID 32611235, 2020).
hemorrhage (23 papers, 2011 to 2025). Loss of blood from the vascular compartment to the exterior or into nonvascular body space as a result of rupture or severance of the blood vessels. "Key factors (e.g., HMOX1 mRNA, hemorrhage location) had small Bootstrap bias (< 12% of original coefficients), significant P-values (all P < 0.05), and concentrated 95% CIs." (PMID 41404462, 2025). "Heme degradation products released after hemorrhage are metabolized by heme oxygenase-1 (HO-1) into biliverdin, iron, and carbon monoxide, leading to free iron accumulation and generation of reactive oxygen species." (PMID 41294825, 2025). "During hemorrhage, a large amount of iron is released from hemoglobin catalyzed by heme oxygenase 1 (HO-1), and inhibition of HO-1 or deletion of HO-1 reduces brain injury after ICH." (PMID 36397619, 2023). "Wang and colleagues measured the levels of heme oxygenase-1 (HO-1), oxyhemoglobin, ferritin, and bilirubin in intrathecal CSF on the 7th day post-hemorrhage." (PMID 36293468, 2022). "In addition, heme oxygenase-1 found in neurons, microglia and astrocytes may alleviate hemorrhage-induced stress injury and reduce brain damage after subarachnoid hemorrhage." (PMID 33328892, 2020).
pulmonary hypertension (23 papers, 2009 to 2026). Increased pressure within the pulmonary circulation due to lung or heart disorder. "m6A modification and YTHDF2 recognition were found on heme oxygenase 1 (Hmox1) mRNA in alveolar macrophages during the development of pulmonary hypertension." (PMID 40662138, 2025). "YTHDF2 can contribute to pulmonary hypertension through the degradation of Hmox1 mRNA, early macrophage polarization, and vascular inflammation." (PMID 40662138, 2025). "In this study, we hypothesized that the major benefits of simvastatin in pulmonary hypertension occur via the heme oxygenase-1 pathway." (PMID 19409105, 2009). "Therefore, a fall in HMOX-1 expression in the lung of young adult lambs from hypoxic pregnancies in the present study suggest programming of reduced vasoactive mechanisms to protect against pulmonary hypertension." (PMID 39882327, 2024). "Among these proteins, we selected HMOX1 (or HO-1) and IFIT3 for confirmation by the semi-quantitative Western blot approach to confirm these findings due to the importance of HMOX1 and EIF2AK2 (or PKR) in the pulmonary field and due to the novelty of IFIT3 in the pulmonary hypertension field." (PMID 33036472, 2020).
retinal degeneration (23 papers, 2017 to 2025). Degeneration of the retina. "To elucidate the molecular mechanism of retinal degeneration caused by excessive HMOX1 levels, we re-analyzed our previous RNA-seq transcriptome data (GSE146176) from neural retinas of albino mice kept under normal or high intensity light conditions." (PMID 33691741, 2021). "Through protein–protein interaction (PPI) network analysis, six hub ferroptosis-related genes (Jun, Stat3, Hmox1, Atf3, Hspa5 and Ripk1) are ultimately identified in a mice model of retinal degeneration induced by light damage." (PMID 40299661, 2025). "In the light-induced retinal degeneration animal model, HMGB2 causes photoreceptor cell death by down-regulating nuclear factor erythroid 2-related factor/heme oxygenase-1 (Nrf2/HO-1) and up-regulating NFκB/NLRP3 signaling inflammatory pathways." (PMID 35269741, 2022). "Our data confirm previous studies that HMOX1 protects photoreceptor cells from light-induced retinal degeneration." (PMID 33691741, 2021). "Basal and induced levels of HMOX1 in retinas are examined during light-induced retinal degeneration in mice." (PMID 33691741, 2021). "Light-induced retinal degeneration leads to photoreceptor degeneration and concomitant HMOX1 induction." (PMID 33691741, 2021). "Here, we test whether HMOX1 has opposing effects during retinal degeneration and investigate the molecular mechanisms behind its pro-apoptotic role." (PMID 33691741, 2021). "Nevertheless, expression of a low dose of recombinant HMOX1 using an AAV8 vector protects against subsequent light-induced photoreceptor cell degeneration, but expression of a high dose of HMOX1 causes photoreceptor cell death and retinal degeneration." (PMID 33691741, 2021). "Hence, to investigate the relationship of retinal degeneration and induction of HMOX1, we exposed light-sensitive two-month-old BALB/c albino mice to light at 15,000 lx for different times." (PMID 33691741, 2021). "In addition, we identified two drugs with protective effects against retinal degeneration, metformin and the fetal hemoglobin inducer TN1, and found that the HMOX1 gene may be associated with this protective effect." (PMID 40837411, 2025). "Thus, a low level of HMOX1 expression as achieved by AAV-mediated gene transfer at a low dose protects against light-induced retinal degeneration while a high level of HMOX1 expression after high dose gene transfer leads to retinal degeneration." (PMID 33691741, 2021). "Based on the fact that retinal degeneration associated with high dose of HMOX1 levels is correlated with upregulation of Ddit3 expression, we finally evaluated whether the induction of DDIT3 might mediate HMOX1-induced photoreceptor degeneration." (PMID 33691741, 2021). "Sulforaphane, an isothiocyanate of plant origin, has shown its therapeutic properties in experimental models of retinal degeneration by activating NRF2, resulting in increased levels of TXN, TXNRD, and heme oxygenase-1 (HO-1)." (PMID 40867647, 2025). "Furthermore, it has been shown that high levels of HMOX1 could induce retinal degeneration." (PMID 40822473, 2025). "Sulforaphane, a major isothiocyanate derived from cruciferous vegetables, has shown its therapeutic effect on retinal degeneration models via the activation of NRF2, resulting in the increased level of TXN, TXNRD, and heme oxygenase-1 (HO-1)." (PMID 36274523, 2022). "Therefore, Hmox1 may play a protective role in the early stages of retinal degeneration." (PMID 34358120, 2021). "Furthermore, sulforaphane, an isothiocyanate from cruciferous vegetables, has demonstrated therapeutic effects in retinal degeneration models by activating NRF2, which upregulates antioxidant proteins like thioredoxin (TXN), thioredoxin reductase (TXNRD), and heme oxygenase-1 (HO-1)." (PMID 40002339, 2025).
retinal degeneration (continued). "Additionally, given the complexity and the degree of crosstalk between various immune pathways, other transcription factors (TFs), such as Hmox1, NFkB, and NFE2L2, might also interact with the C3a-C3ar1 pathway and be involved in retinal degeneration." (PMID 36110094, 2022). "HMOX1 induction has been observed during retinal damage or degeneration, and overexpression of HMOX1 by AAV-mediated gene delivery can partially prevent photoreceptor degeneration and its activity is required for preventing retinal degeneration in a mouse model of RP." (PMID 33691741, 2021).
sickle cell disease (23 papers, 2009 to 2026). Sickle cell anemias are chronic hemolytic diseases that may induce three types of acute accidents: severe anemia, severe bacterial infections, and ischemic vasoocclusive accidents (VOA) caused by sickle-shaped red blood cells obstructing small blood vessels and capillaries. "One notable polymorphism in the HMOX1 gene is rs2071746, where the A>T change is linked to various oxidative stress-related diseases like sickle cell anemia, ischemic heart disease, hypertension, and rheumatoid arthritis." (PMID 38983269, 2024). "Particularly in sickle cell anemia, the rs2071746TT genotype in the HMOX1 gene’s promoter is associated with elevated fetal hemoglobin (Hb F) levels." (PMID 38983269, 2024). "HMOX1 long GT tandem repeats are associated with the occurrence of AKI in sickle cell anemia people." (PMID 35658960, 2022). "Of interest, a polymorphism in the HMOX1 gene was associated with high levels of fetal hemoglobin in Brazilian patients with sickle cell anemia." (PMID 26509275, 2015). "It has been reported that excess heme can increase HO-1 expression and cellular iron to promote cardiac ferroptosis in mice with sickle cell disease, giving us inspiration that heme is possible to be the factor causing HMOX1 overexpression to trigger ferroptosis." (PMID 35498043, 2022). "As, the sickle cell anemia patients show significant oxidative stress due to hemolysis, the study of polymorphisms in the HMOX1 gene may act as a potential independent marker for elevated HbF levels." (PMID 33116199, 2020). "Previous studies have shown that HMOX1 plays a crucial role in hypoxia and infections in myocardial osteosarcoma cells, breast epithelium during mastitis, and cardiomyocytes in sickle cell disease." (PMID 40932981, 2025). "HMOX1 has also been reported as upregulated in two hereditary blood diseases, sickle cell disease and beta-Thalassemia, where NRF2 activation can potentially alleviate disease severity by reducing oxidative damage, inhibiting haemoglobin S polymerization, and promoting foetal haemoglobin expression." (PMID 41109135, 2025). "According to previous studies, Hmox1 exerts a critical effect in ferroptosis by protecting the body from hypoxia and infection of myocardial osteosarcoma cells, breast epithelium in mastitis, and cardiomyocytes in sickle cell disease." (PMID 38532724, 2023).